MYC (MYC proto-oncogene, bHLH transcription factor)
Diseases named in the same sentence as MYC in open-access papers (continued):
Sharing a sentence is not in itself a finding about the gene and the disease.
rhabdoid tumor (14 papers, 2013 to 2025). An aggressive malignant embryonal neoplasm usually occurring during childhood. "Gene set enrichment analysis (GSEA) demonstrated that gene programs, which are deregulated by loss of SMARCB1 in rhabdoid tumors (MYC, cyclin D1 and the pluripotency program) are further upregulatedfollowing SAHA treatment." (PMID 23764045, 2013). "Interestingly SAHA activates tumor pathways, which are already deregulated in rhabdoid tumors (such as MYC, CYCLIND and the pluripotency associated program controlled by EZH2)." (PMID 23764045, 2013). "By methylation profiling, all tumors were classified as rhabdoid tumors with a corresponding subclassification within the MYC, TYR, or SHH AT/RT subgroups." (PMID 35912263, 2022). "Given the reported role of MYC in RT, we analyzed the effect of combined BRD4i/CDK9i on cMYC expression in rhabdoid tumor cell lines." (PMID 29156698, 2017). "To analyze known deregulated pathways in rhabdoid tumors, like RB and MYC, we performed microarray analysis of A204 after treatment with HDAC inhibitor SAHA." (PMID 23764045, 2013). "We analyzed known deregulated pathways in rhabdoid tumors, like cdk4/6-cyclinD-RB- and MYC, using gene set enrichment analysis (GSEA)." (PMID 23764045, 2013). "Having identified an increased DNA repair gene signature in SCCOHT tumors that is likely related to MYC activity, we turned our attention to SNF5-deficient rhabdoid tumors because of the established connection between SNF5 and MYC in cell lines from these cancers." (PMID 40647552, 2025). "Interestingly, MYC inhibition showed the most dramatic impact on rhabdoid cancer cells, in agreement with a recent observation that MYC inhibition effectively restricted rhabdoid tumor growth in vivo." (PMID 35879727, 2022). "Based on these findings, MYC inhibition may be a viable therapeutic in rhabdoid tumor cases with high expression of MYC." (PMID 35892904, 2022). "Considering this, it is interesting to speculate based on our data that MYC contributes to the enhanced genomic stability inherent to SCCOHT and rhabdoid tumors by acting as a regulator of DNA repair gene expression." (PMID 40647552, 2025). "Additionally, combing LDC0000167 with the BRD4 inhibitors-JQ1 or iBET-762 against malignant rhabdoid tumors, down-regulated the anti-apoptotic genes MCL-1, BCL-6 and BTG1 as well as MYC and inhibited cell-proliferation and tumor growth in vitro and in vivo." (PMID 34062779, 2021). "Some pathways drivingoncogenesis are defined in rhabdoid tumors: In SMARCB1 negative tumors oncogenes (including MYC and CYCLIND1) and tumor cascades such as the sonic hedgehog pathway are activated." (PMID 23764045, 2013).
uveal melanoma (14 papers, 2009 to 2023). A melanoma derived from melanocytes of the uveal tract. "More studies at 8q24 loci are needed to explore the association of MYC amplification for tumor progression in uveal melanoma." (PMID 34830903, 2021). "Considering the Harrell’s C indices for MYC copy number gain and BAP1 mutation, we think that both factors affect survival outcomes of uveal melanoma patients independently." (PMID 31848373, 2019). "This locus harbors the oncogenes MYC, a commonly amplified uveal melanoma gene, and PTK2, a regulator of metastasis in uveal melanoma." (PMID 36860651, 2023). "Whether Wnt/β-catenin indeed lies downstream of HES6 in uveal melanoma cells and whether Wnt/β-catenin inhibitors prevent HES6 effects on proliferation and migration or MYC expression remain to be investigated." (PMID 35673577, 2022).
anemia (13 papers, 2016 to 2026). A reduction in the number of red blood cells, the amount of hemoglobin, and/or the volume of packed red blood cells. "Our previous data indicated MYC rs4645948 was conferred with increased risk of anemia and severe leukopenia for NPC patients receiving chemoradiotherapy." (PMID 35990252, 2022). "The generalized linear mixed modeling analyses identified clinical factors associated with concordance: for physician charted assessments, greater numbers of extranodal sites increased agreement with BICR (OR 1.92), while MYC mutation (OR 0.38) and anemia (OR 0.37) reduced agreement." (PMID 41817658, 2026). "For example, anemia related with the gene sets of extracellular region was regulated by hsa-miR-29a, hsa-miR-29b and hsa-miR-29c, and meanwhile MYC and CEBPA regulated the expression of these miRNAs." (PMID 28729650, 2017). "MM patients requiring treatment for their disease have organ damage in the form of anaemia, renal failure and/or lytic bone lesions, which has been shown to be replicated in the Vk*MYC mouse models." (PMID 27599546, 2016). "Importantly, MYC is highly pleiotropic indicating that its deregulation is in close connection with all hematological malignancies, especially anaemia which is a prominent feature of the AAT disease and also with drug resistance." (PMID 33429951, 2021). "Among them, Vk*MYC Tg mice, in which the activation of MYC is under the control of Ig kappa light chain gene regulatory elements, show anemia, osteolytic bone lesion, and kidney damage, resembling human MM symptoms, and the MM cells are transplantable with the reconstitution in BM." (PMID 33374627, 2020). "The AML-bearing mice presented with leukocytosis, anemia, thrombocytopenia, and splenomegaly, and their bone marrow was replete with AML cells, which exhibited robust MYC and MNT expression." (PMID 41140443, 2025). "MYC+RUNX2-DKO leukemic cells were transplantable in secondary recipient mice with the same CD11b−CD11cmid/+B220+Bst2+ immunophenotype, and recipient mice died earlier at 2 weeks post-transplantation (the median survival, 23 days) due to severe anemia and thrombocytopenia." (PMID 30971697, 2019). "Based on the direction of biological regulation mapping MYC, CEBPA, hsa-miR-29a, hsa-miR-29b, hsa-miR-29c and gene sets of extracellular domain could accurately display the occurrence mechanism of the side effect—anemia." (PMID 28729650, 2017).
Cirrhosis (13 papers, 2012 to 2025). A chronic disorder of the liver in which liver tissue becomes scarred and is partially replaced by regenerative nodules and fibrotic tissue resulting in loss of liver function. "In the need for redefining the function of c-MYC in liver fibrogenesis, cirrhosis and end-stage HCC, it is necessary to explore pathways regulated by c-MYC and, ultimately, link these data with clinical outcomes and therapeutic strategies." (PMID 28422055, 2017). "Thus, it is also worth it to investigate whether c-MYC-induced URI1 is involved in sorafenib resistance mechanisms in HCC-B patients with decompensated cirrhosis." (PMID 31739577, 2019). "The present study adds the current evidence in the field by investigating the impact of MYC amplification and ARID1A on prognosis in a population of patients with a low prevalence of cirrhosis and viral hepatitis undergoing liver resection for HCC." (PMID 38536546, 2024). "A previous report indicated the strong link between cirrhosis, HCC and the gene modification and methylation state of c-MYC in human liver tissue." (PMID 28422055, 2017).
endometriosis (13 papers, 2014 to 2025). The growth of functional endometrial tissue in anatomic sites outside the uterine body. "Thus, we excluded a simultaneous upregulation of TWIST1 and MYC that may orchestrate the cellular changes associated with invasion and proliferation in endometriosis." (PMID 26198055, 2015). "The role of “hubs” in these endometriosis-significant interactions was performed by proteins such as MYC (participates in 7 pair interactions), POU3F2 (6 pair interactions) and CTCF (4 pair interactions)." (PMID 41373783, 2025). "While several studies have reported upregulation of c-MYC in the ectopic and eutopic endometrium of patients with endometriosis, PFDN5 expression and potential function remains to be evaluated in this disease." (PMID 38397067, 2024). "While targeting of c-MYC with Omomyc has recently gained substantial interest in the field of cancer research, there has been no recent attempt to evaluate the potential utility in targeting c-MYC for endometriosis treatment." (PMID 38078012, 2023). "Future application of targeting c-MYC in endometriosis treatment and potential pros and cons are then discussed." (PMID 38078012, 2023). "This would be one critical necessary first step in evaluating this c-MYC inhibitor for endometriosis treatment." (PMID 38078012, 2023). "Additional investigation into Akt/PI3K activity and MYC expression are needed to confirm such an increase in aerobic glycolysis in endometriosis tissue." (PMID 31445519, 2019). "Accordingly, in the eutopic endometrium of endometriosis patients, epithelial MYC expression is observed more frequently in patients in the proliferative cycle phase than in the secretory phase (p < 0.001, Chi2 test)." (PMID 26198055, 2015). "MYC is upregulated in the ectopic and eutopic endometrium of patients with endometriosis when analyzed by reverse transcription PCR and IHC." (PMID 26198055, 2015). "Several studies investigating MYC expression in endometriosis observed increased MYC mRNA and protein expression in ectopic and eutopic endometrium from endometriosis patients." (PMID 26198055, 2015). "Previously, we could show a significant downregulation of c-MYC protein expression in the stromal compartment of ectopic endometriosis lesions, suggesting that cells with reduced c-MYC are more prone to survive apoptotic stimuli." (PMID 38203610, 2023). "In endometriosis, the overexpression of MYC is also well established." (PMID 26198055, 2015). "MYC, which is upregulated by estrogens in the uterus by an estrogen response cis-acting element (ERE) in its promoter, is associated with proliferation in endometriosis." (PMID 26198055, 2015). "It seems that a high expression of TWIST1, which was shown to be associated with the stemness marker OCT4 in endometriosis, excludes a high expression of MYC, which is associated with proliferation in endometriosis." (PMID 26198055, 2015). "In our study of 110 endometriosis patients, we discriminated between epithelial and stromal protein expression by using IHC analysis for TWIST1 and MYC." (PMID 26198055, 2015). "The role of EMT and proliferation in the pathogenesis of endometriosis was evaluated by analyzing TWIST1, CDH1 and MYC expression." (PMID 26198055, 2015). "To date, the potential utility of targeting c-MYC as a therapeutic approach for endometriosis treatment has not been reported." (PMID 38078012, 2023). "Lastly, we provide preliminary evidence supporting the potential of targeting c-MYC as a non-hormonal treatment option for endometriosis." (PMID 38078012, 2023). "Although both were upregulated, TWIST1 and MYC were not expressed concurrently, which suggest that in cells with high MYC expression, an additional upregulation of TWIST1 and vice versa seems to provide no further advantage for the development of endometriosis." (PMID 26198055, 2015).
fibrosarcoma (13 papers, 2012 to 2026). A malignant mesenchymal fibroblastic neoplasm affecting the soft tissue and bone. "Remarkably, Mφ-c-Myc-KO mice also show defective tumor angiogenesis and reduced fibrosarcoma development, suggesting that c-MYC expression in TAMs contributes to the development of multiple tumor types." (PMID 23028984, 2012). "However, this mutant has been reported to exhibit a similar half-life to the WT MYC in REF52 cells, or increased stability such as in primary cerebellar granule neuron precursor cells as well as in 2fTGH fibrosarcoma cells compared to WT MYCN and WT MYC, respectively." (PMID 28665315, 2017).
Hodgkins lymphoma (13 papers, 2015 to 2025). A heterogeneous group of malignant lymphoid neoplasms of B-cell origin characterized histologically by the presence of Hodgkin and Reed-Sternberg (HRS) cells in the vast majority of cases. "The annotation results also indicated the elements predicted to regulate MYC harbored SNPs associated with human traits including Hodgkin's lymphoma (rs7826413) and height (rs6470764)." (PMID 35639508, 2022).
renal fibrosis (13 papers, 2016 to 2026). A final common manifestation of a wide variety of chronic kidney diseases characterized by glomerulosclerosis and tubulointerstitial fibrosis. "Other functions included renal fibrosis (SMAD4), renal cell proliferation (PNN), renal cell viability (APP), and hyperplasia (MYC)." (PMID 34063776, 2021).
colorectal adenocarcinoma (12 papers, 2014 to 2025). The most common type of colorectal carcinoma. "PVT1 fusion genes were first described when amplified allele of MYC in colorectal adenocarcinoma cell line showed displacement of Exon 1 and Intron 1 of MYC by PVT1 resulting in DNA rearrangement." (PMID 32117705, 2020). "For example, ovarian MiNEN PN19 is a high-grade sample with a MYC amplification that clustered with TCGA colorectal adenocarcinomas." (PMID 40328872, 2025). "In order to investigate the transcriptional regulation of SNHG15 by MYC, we analyzed colorectal adenocarcinoma RNA-seq data from TCGA, finding that SNHG15 is significantly upregulated in the tumors with high level of MYC expression." (PMID 31014355, 2019). "Similarly, GSEA of an adagrasib-resistant SW837 (KRAS-G12C mutant colorectal adenocarcinoma cell line) CDX model also suggested that MYC targets were among top enriched pathways compared to treatment naïve tumors." (PMID 40316534, 2025). "Gene set enrichment analysis (GSEA) of TCGA COADREAD patient tumors in comparison to solid tissue normal samples confirmed that pro-survival, oncogenic gene sets such as G2M checkpoint, MYC targets, and E2F targets are overexpressed in colorectal adenocarcinoma patient tumors." (PMID 41000734, 2025). "Interestingly, the classification of colorectal adenocarcinoma TCGA samples relative to MYC expression showed that SNHG15 is upregulated in the samples with high levels of MYC expression." (PMID 31014355, 2019). "We could show that in the LS174T and LoVo colorectal adenocarcinoma cell lines c-MYC expression was already significantly reduced at the non-lethal concentration of 0.1 mM of diclofenac, but not in A549 cells." (PMID 38229111, 2024).
intestinal tumor (12 papers, 2012 to 2026). "MYC amplification was significantly linked to intestinal tumors (p = 0.0333)." (PMID 25649416, 2015). "Second, MYC has the highest mRNA expression level in N14-77 polyps, among 28 canine intestinal tumor and normal samples investigated." (PMID 30018743, 2018).
invasive carcinoma (12 papers, 2010 to 2023). A carcinoma that is not confined to the epithelium, and has spread to the surrounding stroma. "In lesions and invasive carcinomas of the serrated route, high c-MYC and SIRT1 levels were associated with K-Ras, B-Raf, or in a minor fraction, with Wnt pathway activation." (PMID 23045412, 2012). "In the majority of cases with KRAS or BRAF mutations, high c-MYC expression was consistently observed in lesions with low grade intraepithelial neoplasia to invasive carcinomas." (PMID 23045412, 2012). "Upon cell transformation, a progressive increase in the number of pSTAT3+ CK14+ MYC+ cells was observed from precursors to invasive carcinoma." (PMID 31438567, 2019). "In invasive carcinomas, we identified two groups with respect to the c-MYC and SIRT1 levels: One group comprised four cases (45%) which displayed negative to low c-MYC expression and negative SIRT1 staining." (PMID 23045412, 2012). "In the somewhat larger invasive tumors, many cells have both high levels of MYC and high levels of Nkx3.1, which suggests that the tight regulation of Nkx3.1 by MYC in the PIN lesions appears to be lost to some degree in the invasive carcinoma lesions." (PMID 20195545, 2010). "In this study, we also examined the interface between PIN lesions and invasive adenocarcinoma lesions in MYC driven mouse models and we have identified a novel histopathologically definable intermediate step in the progression of PIN to micro-invasive carcinoma." (PMID 20195545, 2010). "Finally, our detailed examination of prostate morphology in Lo-MYC (and Hi-MYC) mice uncovered an additional intermediate step (cribriform PIN/CIS) in progression from mouse PIN to invasive carcinoma." (PMID 20195545, 2010). "Hence, unscheduled c-MYC expression together with elevated SIRT1 activity in serrated lesions and invasive carcinomas may repress the two major tumor suppressive mechanisms, apoptosis and senescence and thus support cell survival, expansion and cancer progression." (PMID 23045412, 2012).
laryngeal carcinoma (12 papers, 2011 to 2024). Carcinoma that arises from the laryngeal epithelium. "MYCT1 (MYC target 1), located on chromosome 6q25, was first discovered and cloned by our research group in laryngeal cancer and was once named the C-MYC target from laryngeal cancer cells (MTLC)." (PMID 38172714, 2024). "We first examined the protein levels of the key molecular markers, including cyclin D1, Wnt4, MYC, Wnt7A, and Wnt9A, of the Wnt/β-catenin signaling pathway in laryngeal carcinoma cells." (PMID 33060569, 2020). "It was also proposed that let-7a may be a tumor suppressor in laryngeal cancer by inhibiting cell growth, inducing cell apoptosis and down-regulating oncogene expression; in Hep-2 cells, let-7a induced apoptosis and downregulated RAS and c-MYC protein expression without affecting the mRNA levels." (PMID 22074483, 2011).
primary effusion lymphoma (12 papers, 2011 to 2025). A large B-cell lymphoma located in the body cavities, characterized by pleural, peritoneal, and pericardial fluid lymphomatous effusions and that is always associated with human herpes virus-8 (HHV-8). "Disruption of the IKZF1/3-IRF4-MYC transcriptional axis is of specific importance in MM, as studies have shown that in other diseases, such as primary effusion lymphoma, degradation of IKZF1/3 is uncoupled from lenalidomide-induced suppression of IRF4 and MYC." (PMID 34834536, 2021).